POMC (proopiomelanocortin)
Diseases named in the same sentence as POMC in open-access papers (continued):
Sharing a sentence is not in itself a finding about the gene and the disease.
Obesity (continued). "On the other hand, others and we have reported up regulation of hypothalamic MFN2 protein levels of obese mice, and defective MFN2-expression in POMC or Agrp neurons promotes or prevents obesity in a rodent obese model, respectively." (PMID 29991958, 2018). "Only in rare cases can monogenic etiologies of obesity be identified, such as mutations in genes encoding select hormones (LEP, POMC) or their receptors (LEPR, MC4R)." (PMID 30185666, 2018). "Meanwhile, the genetic deletion of POMC alone is sufficient to produce massive obesity in mice, which is phenocopied in mice harboring the dual deletion of AgRP and POMC." (PMID 30185666, 2018). "Irrespective, our studies point towards the heightened hypothalamic TCPTP levels in obesity resulting in the majority of POMC neurons being inhibited by insulin, to contribute to the increased HGP and fasting hyperglycemia that accompany the obese state." (PMID 30230471, 2018). "Further studies are required to investigate the relative contributions of ERAD and UPR in POMC neurons in the context of diet-induced obesity." (PMID 29457782, 2018). "This point mutation results in a bioinactive form of POMC/ACTH with a clinical phenotype of red hair, obesity and central adrenal insufficiency but with elevated ACTH levels on biochemical testing." (PMID 28739551, 2018). "Most notably, human obesity has been associated with mutations in leptin (LEP), leptin receptor (LEPR), prohormone convertase 1 (PC1), proopiomelanocortin (POMC) and melanocortin-4 receptor (MC4R)." (PMID 30068297, 2018). "show that the anti-obesity 5-HT2CR agonist lorcaserin targets both the POMC circuitry of the hypothalamus and the brainstem nucleus of the solitary tract (5-HT2CRNTS) to mediate appetite suppression." (PMID 30146485, 2018). "Most studies have reported the associations between POMC, MC4R, and HNF4A variants and obesity and MetS-related phenotypes." (PMID 29598821, 2018). "These mainly include genes that are involved in energy balance, appetite regulation, and adipogenesis, i.e., fat mass and obesity-associated protein gene (FTO), and genes in the leptin–proopiomelanocortin pathway and uncoupling protein families." (PMID 28615046, 2017). "The mutated genes, related to obesity, include leptin (LEP), leptin receptor (LEPR), pro-opiomelanocortin (POMC) and melanocortin-4 receptor (MC4R)." (PMID 27894098, 2017). "The ablation of POMC neurons or the depletion of the POMC gene induces marked obesity in animals, while the optical activation of POMC neurons through channelrhodopsin-2 (ChR2) selectively expressed in these neurons diminishes feeding behavior." (PMID 28762946, 2017). "Recent studies reported altered mitochondrial dynamics and decreased mitochondria- endoplasmic reticulum contacts in POMC neurons during diet-induced obesity." (PMID 28762947, 2017). "Taken together, we provide the first direct evidence for a diet-dependent deterioration of Ca2+ homeostasis in POMC neurons during obesity development." (PMID 28762947, 2017). "Conversely, mutations in the POMC, MC3R, or MC4R genes cause common or massive early-onset obesity in humans, further supporting a crucial role for the melanocortin pathway in energy homeostasis." (PMID 28424580, 2017). "In such a context, the characterization of the unidentified neurons capable of modulating POMC/CART neurons in response to leptin can be seen as major challenge of the current research in the neurobiology of obesity." (PMID 28690493, 2017). "More precisely, inactivation of AMPK in POMC neurons induced obesity while SIRT1 in POMC neurons is required for adaptations against diet-induced obesity." (PMID 28424580, 2017). "It is well documented that increased caloric intake causes leptin and insulin resistance in ARH neurons (Könner and Brüning, 2012; Varela and Horvath, 2012), and that glucose sensing of POMC neurons is impaired in obesity." (PMID 28762947, 2017).
Obesity (continued). "In anorexigenic POMC neurons diet-induced obesity (DIO) altered mitochondrial network dynamics and decreased mitochondria-ER contacts by downregulation of MFN2." (PMID 28762947, 2017). "Homozygous loss of MC4R function, and homozygous loss of proopiomelanocortin gene function, a preprohormone precursor of the endogenous MC4R agonist have both been reported in patients with early onset obesity." (PMID 28829041, 2017). "A GWAS which identified 14 known obesity susceptibility variants and 18 new loci that were associated with BMI found that some of these loci are mapped at the LEP–POMC pathway, i.e., LEP and its receptor LEPR, POMC and MC4R." (PMID 28615046, 2017). "Taken together, we provide the first direct evidence for a diet-dependent deterioration of Ca2+ homeostasis in POMC neurons during obesity development resulting in impaired function of these critical energy homeostasis-regulating neurons." (PMID 28762947, 2017). "We reveal that a large sex difference in physical activity, energy expenditure and the development of obesity is driven by this subpopulation, which constitutes approximately 40% of all POMC neurons in the hypothalamic arcuate nucleus." (PMID 26977396, 2016). "Using an outbred model of diet-induced obesity we show that defective regulation of hypothalamic POMC is the earliest marker distinguishing obesity-prone from obesity-resistant mice." (PMID 27373214, 2016). "We show that the anomalous regulation of hypothalamic POMC precedes inflammation and is a determining factor leading to the progression of obesity." (PMID 27373214, 2016). "Several studies suggest modification mechanisms of early life stress (ELS) and diet-induced obesity (DIO) programming in the hypothalamic regions with populations of POMC-expressing neurons." (PMID 27147943, 2016). "It is worth noting that POMC neurons have been reported to play a fundamental role in the development of obesity-induced hypertension." (PMID 28006821, 2016). "Treatment with a 5-hydroxytryptamine 2c receptor (5-HT2CR) agonist, such as the new obesity medication lorcaserin (Arena Pharmaceuticals), restores diminished POMC neuron function and improves obesity." (PMID 26977396, 2016). "The early inhibition of hypothalamic POMC was sufficient to transform obesity-resistant in obesity-prone mice." (PMID 27373214, 2016). "Here, we showed that knockout of IRE1α in POMC neurons decreases fat mass and protects mice from HFD-induced obesity and obesity-related metabolic disorders, the effects of which are caused by increased energy expenditure." (PMID 27558934, 2016). "Taken together, these results suggest that defective regulation of POMC expression, which leads to a change of β-endorphin levels, is the earliest hypothalamic defect leading to obesity." (PMID 27373214, 2016). "Conversely, POMC expression was down-regulated in DIO rats when obesity was present from several weeks and, also in this case, the authors found a consistent change of DNA methylation at the gene promoter for POMC." (PMID 27554849, 2016). "Central among these integration nodes are the brain pro-opiomelanocortin (POMC) peptides, perturbations of which disrupt energy balance and promote severe obesity." (PMID 26977396, 2016). "Thus studying POMC signaling in more accessible systems such as peripheral blood cells might be reflective of central events and can provide insight into signaling mechanisms underlying obesity." (PMID 26940669, 2016). "Further, deletion of Ift88 in POMC-expressing cells in mice resulted in hyperphagia and obesity, demonstrating that ciliary function specifically of POMC-expressing neurons is crucial to the neuronal circuitry that controls appetite." (PMID 27482817, 2016). "Excessive production of TGF-β by POMC neurons was found to promote hypothalamic inflammation and type 2 diabetes in obesity and during aging." (PMID 27609221, 2016).
Obesity (continued). "Mutations of the leptin, leptin receptor, POMC, and MC4-R genes lead to severe obesity in rodents and in humans, underscoring the importance of central leptin-melanocortin signaling for the regulation of energy balance." (PMID 27609221, 2016). "Conversely in anorexigenic pro-opiomelanocortin POMC neurons, Mfn2 selective deletion causes severe obesity and leptin resistance probably by mediating ER stress-induced leptin resistance." (PMID 25904870, 2015). "The aim of the present study was todetermine the possible association of five single-nucleotide polymorphisms (SNPs)located in the IGF2, LEPR, POMC,PPARG, and PPARGC1genes with obesity orobesity-related risk phenotypes." (PMID 25923461, 2015). "Monogenic mutations such as those described for LEP, LEPR, POMC, and MC4R cause only a minority of obesity cases whereas in most individuals obesity is based on a polygenic predisposition amplified by an obesogenic Western lifestyle." (PMID 26470795, 2015). "Activation of POMC neurons during caloric intake protects against diet-induced obesity whereas activation of AgRP neurons informs the body to store energy during fasting." (PMID 26441839, 2015). "In addition to genetic polymorphisms in POMC, epigenetic variations could contribute to an individual's risk of obesity." (PMID 25954145, 2015). "Our work suggests that the KCNQ channels in POMC neurons would be an alternative therapeutic target against obesity and type 2 diabetes as they are regulated by anorexigenic neurotransmitters and adipokines such as serotonin and apelin." (PMID 25782002, 2015). "As above, this reduction of POMC under AMPK activation should be understood in terms of obesity or nutrient-sufficient status." (PMID 25634597, 2015). "Homozygous Sim1 mice die perinatally, but heterozygous mutants exhibit hyperphagic obesity, increased body fat percentage, as well as higher levels of POMC expression and resistance to α-MSH." (PMID 25825681, 2015). "The relevance of miRNAs in the function of melanocortin pathways has been recently highlighted by the deletion of Dicer in POMC-expressing cells which led to a postnatal ablation of POMC neurons resulting in obesity." (PMID 25999818, 2015). "Two recent studies have used Dicer knockout strategy to delete POMC-neurons in the hypothalamus, and reported the development of obesity in parallel to cell death within the first 6 weeks of age." (PMID 25629159, 2015). "In accordance with this aspect, it has been shown that the disruption of the POMC and melanocortin receptor 4 (MC4R) genes in mice models causes obesity, while MC3R gene-deficient mice have normal food consumption but accumulate fat." (PMID 25999818, 2015). "Clinically, disruption of POMC, PCSK1, BDNF, and NTRK2 is associated with severe early-onset obesity." (PMID 25806089, 2015). "Leptin-deficient POMC gene mutation, MCR4 gene mutation need also to be considered among the monogenic causes of early-onset obesity." (PMID 25541898, 2014). "Moreover, obesity is associated with abnormal synaptic transmission in hypothalamic POMC neurons, raising the possibility that aberrant synaptic reorganization and remodeling may contribute to the pathogenesis of obesity and obesity-associated metabolic disease." (PMID 25127258, 2014). "We first sought to evaluate the contribution of ARC POMC to the appetitive effects of 5-HT obesity medications." (PMID 25051442, 2014). "In hypothalamic neurons expressing pro-opiomelanocortin (POMC) the age-dependent up-regulation of KATP channels causes hyperpolarization and neuronal silencing, contributing to obesity of aged animals." (PMID 25221474, 2014). "For instance, POMC methylation can be altered by alcohol intake in mice and humans and with phenotypes such as obesity." (PMID 24112369, 2014). "Ablation of POMC neurons in the ARC results in hyperphagia and obesity in mice; in contrast, acute excitation of POMC neurons decreases food intake." (PMID 25127258, 2014).
Obesity (continued). "DIO rats fed a chow diet display increased inhibitory inputs to POMC neurons compared to obesity-resistant DR rats." (PMID 23543895, 2013). "A more complete understanding of the POMC neural network is critical to determine its function in obesity and related metabolic disorders." (PMID 23440036, 2013). "Over the past 15–20 years, mutations in a number of genes including leptin (LEP), leptin receptor (LEPR), pro-opiomelanocortin (POMC) and melanocortin-4 receptor (MC4R) have been associated with monogenic obesity." (PMID 23306188, 2013). "Serotonin 2C receptors (5-HT2CRs) expressed by arcuate POMC neurons are important in mediating the anti-obesity and anti-diabetic effects of serotonin." (PMID 23734095, 2013). "In the arcuate nucleus, enhanced PIP3 signaling and increased KATP channel activity in POMC neurons led to hyperphagia and diet-induced obesity at least in part by blunting the acute effects of leptin and insulin." (PMID 23734095, 2013). "Consistent with a functional role for autophagy in POMC neurons, conditional deletion of essential autophagy genes, such as the autophagy-related gene (Atg) 7, results in obesity and impaired glucose homeostasis." (PMID 23543895, 2013). "Direct injection of pharmacological activators of AMPK into the hypothalamus promotes feeding, whereas disruption of AMPKα2 in neurons expressing anorectic POMC-derived peptides leads to obesity due to reduced energy expenditure and increased food intake." (PMID 24209692, 2013). "In fact, selective ablation of Arc POMC neurons mimics the phenotype of the global POMC-null mice, producing increased food intake and reduced energy expenditure, resulting ultimately in obesity." (PMID 24101924, 2013). "Secondly, we found that genetically-driven over-expression of LepRb selectively in arcuate POMC neurons is sufficient to accelerate development of obesity in HFD mice." (PMID 22276206, 2012). "Linkage analysis confirmed the trend (maximum LOD at D2S2337 = 2.03) towards linkage between polymorphic markers around POMC and obesity." (PMID 23028917, 2012). "Secondly, we find that over-expression of LepRb selectively in hypothalamic POMC neurons is sufficient to accelerate development of diet-induced obesity." (PMID 22276206, 2012). "Moreover, POMC deficiency itself may contribute to the obesity found in our model." (PMID 22558467, 2012). "Reduced POMC satiety signalling leads to obesity in the clinic and in animal models of obesity, for example, POMC mRNA expression is attenuated in genetically obese Zucker rats, tubby mice (tub gene mutation) and diet-induced obese mice." (PMID 22438946, 2012). "Recessive forms of obesity caused by homozygous / heterozygous compound loss of function mutations in five genes (LEP, LEPR, POMC, PCSK1 and MC4R) have been reported to date." (PMID 22043164, 2011). "We monitored the longitudinal course of body weight gain and obesity development in HFD-fed POMC/HIFβlox/lox mice versus controls." (PMID 21814490, 2011). "Compared to mice fed the control diets, the expression of leptin in fat tissue and leptin-R and POMC in the hypothalamus was higher in the diet-induced obesity (DIO) mice, and the n-3 PUFAs in the diets reversed these elevated expression levels." (PMID 21609458, 2011). "Compared to HFD-fed control mice, HFD-fed POMC/HIFβlox/lox mice gained body weight more rapidly and displayed obesity in an exacerbated manner." (PMID 21814490, 2011). "For example, POMC-neuron-specific SIRT1 knockout mice display hypersensitivity to diet-induced obesity; a defect brought on by reduced sympathetic nerve activity and brown adipocytes content selectively in one visceral fat depot: the perigonadal fat." (PMID 21464518, 2011). "POMC knockout (POMC-/-) mice models show a similar phenotype with adrenal insufficiency, marked obesity and altered pigmentation." (PMID 21860632, 2011).
Obesity (continued). "Knockout of SIRT1 in pro-opiomelanocortin (POMC) neurons caused reduced energy expenditure in mice and then hypersensitivity to diet-induced obesity." (PMID 21738790, 2011). "The importance of POMC in the appetite pathway has made it a strong candidate gene for obesity in humans and carcass traits in livestock." (PMID 21205304, 2011). "To further elucidate the significance of hypothalamic HIF inhibition in obesity development, we maintained POMC/HIFβlox/lox mice and the littermate controls under high-fat diet (HFD) feeding since weaning." (PMID 21814490, 2011). "In humans, genetic linkage studies have identified chromosome 2p22 (region encompassing the POMC gene) as the site of gene or genes influencing common obesity." (PMID 21860632, 2011). "If this prediction is true, in addition to be a key molecular component of defensive mechanisms against diet-induced obesity SIRT1 in POMC neurons will also need to be considered as a critical regulator of lifespan." (PMID 21464518, 2011). "The mechanisms for how saturated fat and sugar-based beverages contribute to human obesity are clearly in rats on an HF choice diet, plasma leptin concentrations and proopiomelanocortin mRNA increased and neuropeptide Y mRNA decreased." (PMID 21235803, 2011). "Mutations that inactivate proopiomelanocortin (POMC) have been described in children with adrenal insufficiency, early onset obesity and sometimes along with fair skin and red hair." (PMID 21274298, 2009). "Defects in the genes for leptin, leptin receptor, proconvertase 1, pro-opiomelanocortin (POMC) and the melanocortin receptors MC3R and MC4R have been associated with obesity." (PMID 19309531, 2009). "For instance, although the selective ablation of leptin receptors in POMC neurons of the arcuate nucleus results in obesity, it is less pronounced than in mice that globally lack leptin receptor." (PMID 17448988, 2007). "POMC deficiency in mice and humans and PC1 homozygous mutations in humans are characterised by adrenal failure, early-onset obesity and, with POMC mutations, altered pigmentation and tall stature." (PMID 17764572, 2007). "POMC heterozygosity has also been found to correlate with obesity in mice and humans, to a lesser extent than the homozygous state." (PMID 17764572, 2007). "Recently, several missense mutations have been identified in human β-MSH, associated with early-onset human obesity, as well as a cleavage site mutation preventing processing of POMC to β-MSH, which is also associated with human obesity." (PMID 17764572, 2007). "POMC knockout mice develop hyperphagia, insulin resistance, and obesity." (PMID 40136445, 2025). "While IRS2 deletion in LepRb neurons caused leptin resistance and obesity in mice, its ablation in POMC neurons did not significantly affect metabolic balance." (PMID 41251447, 2025). "For example, in hypothalamus of aged mice, Solute carrier family 7 member 14 (SLC7A14) expression in decreased, and overexpression of SLC7A14 in hypothalamic POMC neurons alleviated impaired lipolysis in white adipose tissue of aged mice, thereby alleviating aged-dependent obesity." (PMID 41037185, 2025). "In contrast, rare case reports highlight monogenic obesity linked to leptin, LEPR, and POMC genes." (PMID 40077044, 2025). "Consistently, SOCS3 overexpression in POMC neurons leads to leptin resistance and mild obesity." (PMID 41251447, 2025). "Recessive forms of severe obesity were identified, caused by homozygous or compound heterozygous mutations in the following genes: LEP (leptin), LEPR (leptin receptor), BBS1 and BBS10 (Bardet–Biedl syndrome), and POMC (pro-opiomelanocortin)." (PMID 40149731, 2025). "Moreover, chronic mTOR activation in POMC neurons during aging can paradoxically lead to hyperphagic obesity, suggesting that the effect of mTOR depends on the dosage and duration of its activation." (PMID 41516046, 2025).